METTL3 (methyltransferase 3, N6-adenosine-methyltransferase complex catalytic subunit)
Diseases named in the same sentence as METTL3 in open-access papers (continued):
Sharing a sentence is not in itself a finding about the gene and the disease.
tumor (continued). "In breast cancer, METTL3 inhibits E-cadherin expression through m6A modification of EZH2, thereby inducing EMT to promote tumor invasion and metastasis." (PMID 39289775, 2024). "METTL3 and FTO are two of the most extensively studied m6A modifying enzymes during tumor development." (PMID 38711100, 2024). "Silencing the Caprin-1 gene can inhibit EC cell proliferation and glycolysis, as well as reduce the expression of METTL3 and the tumor-related protein WTAP, thereby, affecting tumor growth." (PMID 39010066, 2024). "In HCC, reduced m6A modification of MTF1 mediated by METTL3 acetylation leads to enhanced MTF1 expression, thereby promoting cell proliferation and tumor progression." (PMID 39229278, 2024). "Studies on methyltransferases in kidney cancer, such as ccRCC, demonstrate that both METTL3 and METTL14 play as tumor suppressors." (PMID 39136000, 2024). "We xenografted TetO Control and METTL3-KD SK-N-FI and CHLA-90 cells into immunocompromised mice and measured the effect on tumor formation following DOX induction." (PMID 38180812, 2024). "Several studies have demonstrated that the expression levels of METTL3 and METTL14 are elevated in PCa as compared to normal tissues, acting as tumor promoting driver." (PMID 39268470, 2024). "YTHDF1 recognizes m6A modification of JAK1 mRNA in Tumor-infiltrating myeloid cells mediated by METTL3, and METTL3-m6A-YTHDF1 enhances the translation of JAK1 mRNA, subsequently promoting STAT3 phosphorylation and tumor growth in mice." (PMID 39726589, 2024). "Akin to METTL3, ALKBH5 also influences the response to anti-PD-1 therapy by regulating lactate levels and the accumulation of suppressive immune cells within the tumor microenvironment." (PMID 39199429, 2024). "In conclusion, these results suggest that the METTL3-YTHDC2 axis regulates the stability of LINC00894 mRNA in an m6A-dependent manner and subsequently inhibits tumour malignancy through the Hippo signalling pathway." (PMID 38291427, 2024). "For example, in HCC, as METTL3 expression increases, SOCS2 undergoes increased m6A modifications to promote tumor development." (PMID 38613157, 2024). "METTL3‐mediated m6A modification decreases the expression of IFFO1, a novel tumor suppressor, via affecting mRNA stability to promote tumor development and cisplatin resistance in ovarian cancer." (PMID 39006762, 2024). "The changes in these down-stream target genes further support the claim that METTL3 and METTL14 have tumor suppressor functions in GSCs." (PMID 38398118, 2024). "Nevertheless, in certain cancers, METTL3 and METTL14 demonstrate divergent effects on tumor progression." (PMID 38965238, 2024). "The results of qPCR showed that METTL3 and IGF2BP3 were significantly overexpressed in the tumor cells, while YTHDC2 was significantly downregulated (p < 0.05)." (PMID 39717046, 2024). "Research has confirmed that in bladder cancer (BCa), METTL3 also regulates the PI3K/AKT pathway, which is involved in tumor angiogenesis." (PMID 39295872, 2024). "Nevertheless, recent investigations reveal inconsistent expression levels and prognostic significance of METTL3 and METTL14 across various tumor types, challenging their consistent functional engagement in neoplastic contexts." (PMID 38965238, 2024). "Using the METTL3 inhibitor STM2457 inhibits TLR9-induced B cell proliferation and immunoglobulin secretion, and opposes TLR9-induced immune responses to assist tumor cell immune escape." (PMID 38537697, 2024). "Conversely, ZNF750, a tumor suppressor in NPC, is destabilized by METTL3-mediated m6A modification, leading to reduced FGF14 expression and diminished apoptosis-promoting effects." (PMID 39695216, 2024). "Recent studies have revealed that patients with a high expression of METTL3 and cluster of differentiation 33+ (CD33+) myeloid‐derived suppressor cells (MDSCs) in their CC tumour tissues exhibit a marked contrast to that in adjacent tissues." (PMID 38332508, 2024).
tumor (continued). "Most studies on methyltransferases in bladder cancer claim that METTL3 and METLL14 are oncogenes and tumor suppressors, respectively." (PMID 39136000, 2024). "METTL3 targets ANGPTL3 and downregulates its expression, which is conducive to tumor growth, proliferation, migration, and invasion." (PMID 39678510, 2024). "The methylation of HDGF mRNA mediated by METTL3 enhances mRNA stability and was directly recognized by the m6A reader IGF2BP3 that bound to the m6A site of HDGF mRNA, which facilitates subsequent tumor growth and liver metastasis in GC." (PMID 39009956, 2024). "Among the changes, oncogenes such as ADAM19, EPHA3, and KLF4 showed increased expression, but tumor suppressors like CDKN2A and BRCA2 demonstrated decreased expression by inhibition of METTL3- or METTL14." (PMID 38398118, 2024). "The expression of METTL3 is higher in squamous cell carcinoma (SCC) and its ablation impairs the cells' ability to form tumours." (PMID 39624739, 2024). "The METTL3 and FTO-related tumor signaling pathways and small molecule targeted drugs have been abundantly reported." (PMID 38711100, 2024). "Accordingly, targeting METTL3 down-regulated ABCC2 in cytomembrane, thereby reducing the efflux of chemo-drugs and enhancing their anti-tumor efficacy." (PMID 39309428, 2024). "Now that we had found that METTL3 targets SRPK1 and promotes tumour growth in LUAD, the mechanism by which SRPK1 influenced LUAD progression was further explored." (PMID 39095708, 2024). "The data form GENT indicated an upregulation in the expression of METTL3, RRM2B, OPA1 and IGF2BP2 in CRC tumor tissues compared with normal tissues." (PMID 38549713, 2024). "In experiments with tumor xenografts of the HGC-27 and NCI-N87 cell lines, METTL3 overexpression promoted increases in tumor volume and weight in vivo." (PMID 39678510, 2024). "Taken together, these findings suggest that METTL3 and YTHDF2 are both crucial for anti‐tumour immunity, and YTHDF2 probably functions as a downstream executed reader of the tumour‐killing effect of STM2457 treatment." (PMID 39568154, 2024). "METTL3 enhances ribosomal translation efficiency through the METTL3/m6A/JAK1/STAT3 axis and facilitates tumor immune evasion." (PMID 38879589, 2024). "Analysis of the TCGA database showed that in addition to METTL3 and METTL14, the expression of the novel “m6A writer” METTL16 was also decreased in tumor tissue." (PMID 38334797, 2024). "For further evaluation of METTL3 in the HPV vaccine against csCC, xenograft tumor experiments were performed." (PMID 38030537, 2024). "Recent evidence confirms that METTL3 promotes PCBP2 stability, inhibits apoptosis, and accelerates tumor metastasis in gliomas." (PMID 39033180, 2024). "In NPC, METTL3-mediated m6A modification reduces ZNF750 expression, weakening its tumor-suppressor function in the ZNF750-FGF14 axis, which inhibits apoptosis and promotes NPC growth." (PMID 39695216, 2024). "Currently, mainstream studies have confirmed the high expression of METTL3 in CRC, and METTL3 is closely related to tumor immune escape, glucose metabolism and drug resistance of CRC 15,16,17,18." (PMID 39132158, 2024). "As a result, in CRC, METTL3, METTL14, WTAP, IGF2BP3, YTHDC1, and FTO orchestrate tumor angiogenesis through diverse pathways and mechanisms, thereby affecting the initiation, progression, and prognosis of CRC." (PMID 39295872, 2024). "In summary, the m6A writers METTL3 and METTL14 play important roles in the occurrence and development of tumors by regulating specific targets or pathways that affect tumor angiogenesis." (PMID 39295872, 2024). "Among m6A writers, METTL3 and METTL14 are primarily investigated for their roles in tumor angiogenesis." (PMID 39098905, 2024).
tumor (continued). "As m6A modification in lncRNAs plays a critical role in tumor epigenetic regulation, we further analyzed the relevance of TUG1 and the m6A methyltransferase METTL3." (PMID 38981064, 2024). "It was proved that METTL3 contributed to an increase in SOX2 transcripts, the key molecule in maintaining the initiating properties of tumor cells, in an m6A-IGF2BP2-dependent mechanism in CRC tumorigenesis." (PMID 37152066, 2023). "A recent study indicated that METTL3-mediated m6A modification promoted PD-L1 expression, inhibited CD8 + T cell infiltration, and induced tumor cell immune evasion in NSCLC." (PMID 36810108, 2023). "Mediated by YTDHF2, METTL3/METTL14 knockdown stabilizes STAT1 and Irf1 mRNAs, and promotes IFN‐γ‐STAT1‐Irf1 signaling, which in turn sensitizes tumor cells to PD‐1 inhibition." (PMID 36810108, 2023). "Although most studies provide evidence that METTL3 contributes to the proliferation and progression of RCC, reports have shown a tumour suppressor role of METTL3." (PMID 37284313, 2023). "High expression of METTL3 enhances PDL1 RNA stability and expression level, which facilitates resistance to CD8+ T-cell toxicity and boosts tumor immune escape in vitro and in vivo." (PMID 37996892, 2023). "Both METTL3 and YTHDF2 are positive regulators of NK cell functions, including maintaining the homeostasis, maturation, survival, anti-tumor and anti-viral activity." (PMID 36810281, 2023). "Immunohistochemistry assay showed that CAFs increased the expression of METTL3 and RAC3 in tumor tissues." (PMID 37056933, 2023). "METTL3 promoted HMGA1 expression in an m6A-dependent manner, which induced tumor cell proliferation and tumor growth in CRC." (PMID 37152066, 2023). "CCK-8 assays presented that STAD cells viability was weakened in response to attenuation of METTL3 levels, while ANGPTL3 small interfering RNA partially increased the viability of tumor cells depleted by METTL3 silencing." (PMID 37344779, 2023). "Immunohistochemistry staining of GLI1, METTL3/14, and IGF2BP2 also confirmed that inhibitors against GLI1 or METTL3 decreased protein levels of GLI1, METTL3/14, and IGF2BP2 in tumor samples." (PMID 37149646, 2023). "Enhanced m6A modification mediated by METTL3 accelerates translation of CDC25B and increases the proportion of tumor cells in G2/M stage, leading to malignant cancer growth." (PMID 37996892, 2023). "In some other independent studies on the same cancer, METTL3 and METTL14 also have an opposite effect on tumor process." (PMID 36970605, 2023). "In multiple myeloma, METTL3 increases YY1 expression and promotes tumor progression by enhancing the RNA stability of YY1." (PMID 37996892, 2023). "We believe that METTL3 or FTO inhibitors can significantly inhibit downstream targets expression in tumors with high METTL3 or FTO expression, thereby inhibiting tumor proliferation and metastasis." (PMID 39872957, 2023). "METTL3 methylates pri-miR-221-3p mRNA to increase miR-221-3p expression and negatively regulate HIPK2, a tumor suppressor that can be activated by doxorubicin." (PMID 37264402, 2023). "The authors corroborated previous findings by showing that METTL3 levels are upregulated in GBM patient samples and that, in mice models, METTL3-knockdown suppressed tumour growth." (PMID 37444417, 2023). "On the other hand, WTAP and METTL3 are abundantly expressed in HCC and are necessary for tumor cell proliferation." (PMID 37777158, 2023). "METTL3 knockdown or miR-146b ablation alone significantly increases the TAM population, reduces T cell infiltration, and promotes tumor progression." (PMID 37402945, 2023). "METTL3 and METTL14 knockdown GSCs in a mouse model of GBM produced larger tumours with poorer survival rates." (PMID 37444417, 2023).
tumor (continued). "METTL3 knockdown in NSCLC cells dramatically inhibited cell migration and invasion, and suppressed tumor growth in vivo." (PMID 37056933, 2023). "To decipher the molecular mechanism of METTL3-induced NAFLD-HCC, we performed RNA-seq of NAFLD-HCC tumor tissues from Mettl3LKI and wild-type mice." (PMID 37586322, 2023). "Accumulating evidence has underscored the m6A writer METTL3, exhibited an oncogenic potentiality in CRC tumorigenesis recently, wherein it accelerated tumor growth and metastasis through suppressing the expression of YPEL5 in an m6A-YTHDF2-dependent manner." (PMID 37626036, 2023). "In the TIME, depletion of METTL3, or METTL14 depletion within CRC tumors, increases cytotoxic tumor-infiltrating CD8+ T cells and secretion of cytokines such as IFN-γ, CXCL9 and CXCL10, hence sensitizing tumors to PD-1 antibody treatment." (PMID 37015927, 2023). "Mechanistically, YTHDF2 accelerates UBXN1 mRNA degradation by recognizing METTL3-mediated m6A modification sites on UBXN1 mRNA, activating NF-κB and accelerating tumor progression." (PMID 37964279, 2023). "METTL3, FTO, and IGF2BP2 have been shown to function as tumour promoters through the C-myc pathway in an m6A-dependent manner in a range of cancers." (PMID 37444417, 2023). "Subsequent inhibition of METTL3 using a novel small molecule inhibitor, STM2457, significantly impeded tumor growth in LIHC cell lines, spheroids, and xenograft tumor model." (PMID 38012755, 2023). "Subsequently, we evaluated the expressions of proliferation marker Ki67, METTL3 and STAT3 in tumor tissues by IHC staining and Western blotting assay." (PMID 37231451, 2023). "In pancreatic cancer, METTL3 synergistically induces SMS expression with IGF2BP3 and promotes AKT phosphorylation, thus enhancing tumor cell proliferation." (PMID 37996892, 2023). "Increased m6A mediated by METTL3/METTL14 promotes tumorigenesis and tumor metastasis by regulating the stability and translation of oncogenic mRNA in several epithelial cancers." (PMID 37891533, 2023). "Another study reported that METTL3 enhanced the expression of the lipogenesis-related lncRNA LINC00958 in HCC, and the latter promoted lipogenesis and tumour progression." (PMID 36859310, 2023). "In ocular melanoma, down-regulated METTL3-mediated m6A modification leads to attenuated YTHDF1-mediated translation of tumor suppressor HINT2, which promotes tumor progression." (PMID 36830614, 2023). "Consistently, METTL3 knockout inhibited NAFLD-HCC development, as shown by reduced AFP and MRI measurements and the reduced tumor number (p = 0.019) and size (p = 0.042) at sacrifice." (PMID 37586322, 2023). "METTL3 induces GLUT1 translation to promote glucose uptake and lactate production, leading to the activation of mTROC1 signaling, thereby promoting tumor progression." (PMID 37063421, 2023). "The biological activities of METTL3 in CSCC cells were evaluated by CCK-8, colony formation, transwell, wound healing, and xenograft tumor assays, respectively." (PMID 36710350, 2023). "Recent studies demonstrated that METTL3 indirectly promotes HMGA2 expression by regulating the m6A modification of circHPS5 and MALAT1 in tumor cells." (PMID 36945110, 2023). "In general, METTL3, METTL14, IGF2BP1, FTO, and ALKBH increase the level of PD-L1 on the membrane and thereby promote tumor cell immune escape." (PMID 37485079, 2023). "METTL3 upregulation in gastric cancer stimulated m6A modification of HDGF mRNA and enhanced HDGF mRNA stability, resulting in elevated tumor angiogenesis and glycolysis." (PMID 38001065, 2023). "Functionally, METTL3 knockdown drastically inhibited CRC stemness in vitro and suppressed CRC growth and metastasis in cell-based and PDX-based subcutaneous tumor models." (PMID 37152066, 2023). "Methyltransferase-like 3 (METTL3), a key member of the m6A methyltransferase complex, is upregulated in multiple human malignancies and plays a role in regulating tumor migration." (PMID 36348020, 2023).
tumor (continued). "The analyses enabled us to identify the critical pathways affected by METTL3 inhibition in LIHC, including pathways related to cell cycle, metabolism, tumor survival and metastasis." (PMID 38012755, 2023). "In hepatocellular carcinoma, lnc-CTHCC, stabilized by METTL3/IGF2BP1/IGF2BP3 via m6A modification, promotes tumor initiation and development by binding hnRNPK and activating YAP1 transcription." (PMID 37280679, 2023). "Unexpectedly, METTL3 and METTL14 showed dissimilar effects on tumor-infiltrating CD8+ T cell in the TME of breast cancer 112,113." (PMID 37928272, 2023). "In gliomas, METTL3 induces the m6A modification and degradation of UBXN2 RNA in concert with YTHDF2, activating the downstream NF-KB signaling pathway and boosting tumor metastasis." (PMID 37996892, 2023). "The expression of METTL3/14 can synergize with ICI therapy by regulating METTL3/14 expression, potentially enhancing the anti-tumor response." (PMID 38187373, 2023). "Specific inhibitors of m6A regulators have demonstrated exciting anti-tumor effects, including inhibitors of METTL3, FTO, ALKBH5, IGF2BP1, while the therapeutic effects of METTL3 activators remain unverified." (PMID 36810281, 2023). "METTL3 knockdown inhibited SOX2 expression, enhanced the sensitivity of tumor cells to γ-radiation in vitro, and inhibited the growth of GBM cells in mice, thus playing a carcinogenic role." (PMID 37964279, 2023). "Our hepatocyte-specific Mettl3 knockin model and the whole-body Mettl3+/− knockout model suggest that METTL3 promotes NAFLD-HCC, particularly at the tumor stage." (PMID 37586322, 2023). "Based on available limited data, though METTL3 has a preference to exert an oncogenic effect, it is worthwhile mentioning that METTL14 exhibits dual effects but tends to present a protective, tumour‐suppressing role in cancers." (PMID 36162823, 2023). "Numerous studies have previously demonstrated the close association between MAC and cancer, particularly in GI cancers, where METTL3/14, a component of MAC, exerts various effects on tumor progression, including proliferation, growth, invasion, and metastasis." (PMID 38187373, 2023). "Our results suggested that aberrant METTL3 expression was essential for the malignant progression of STAD, and its presence contributed to tumor cells growth and metastasis." (PMID 37344779, 2023). "On one hand, inhibition of METTL3 or METTL14 expression can reduce m6A level, enhance GSCs growth and self-renewal in vitro, as well as promote tumor-forming ability of GSCs in vivo." (PMID 36683086, 2023). "Among the three major components of the writer complex, only METTL3 was upregulated in LUAD as determined by ELISA; METTL14 and WTAP were expressed at similar levels in adjacent and tumor tissues." (PMID 35078505, 2022). "m6A regulators, such as methyltransferase-like 3 (METTL3), have been reported to execute an m6A-dependent modification of noncoding RNAs (ncRNAs) involved in tumor biological processes." (PMID 35757505, 2022). "More strikingly, the combination of shMETTL3 and cisplatin exhibited the most profound tumor inhibition effect on CAL27-A, suggesting that silencing METTL3 enhanced the therapeutical effect of cisplatin on arecoline-transformed OSCC." (PMID 36429032, 2022). "And in mechanism, IFN-γ-Stat1-Irf1 signaling was activated after the depletion of METTL3 and METTL14, leading to the increased secretion of IFN-γ, and finally enhanced the CD8+T cell-mediated anti-tumor response in the tumor microenvironment." (PMID 36058919, 2022). "The cellular models based on ccRCC cell lines such as 786-O and ACHN, were established by operating METTL3 and HHLA2 via knockdown or overexpression, followed by in vitro cellular function studies and in vivo subcutaneous transplantation tumor model." (PMID 35794583, 2022).